MTOR (mechanistic target of rapamycin kinase)
Diseases named in the same sentence as MTOR in open-access papers (continued):
Sharing a sentence is not in itself a finding about the gene and the disease.
hepatocellular carcinoma (continued). "We have provided evidence that HBx activates IKKβ, which leads to inactivation of TSC1 and activation of mTOR/S6K1 and to the production of angiogenesis factor VEGF-A in HBx expressing hepatoma cells and liver tissues of HBx transgenic mice." (PMID 22848663, 2012). "We found that HBx modulated IKKβ/TSC1/mTOR signaling and up-regulated cell proliferation and VEGF production in both unstimulated and TNF-α-stmulated hepatoma cells." (PMID 22848663, 2012). "Zinc has been shown to modulate FoxO signaling in human hepatoma cells and in mouse embryonic stem cells zinc stimulates DNA synthesis through the PI3K/Akt, MAPKs and mTOR pathways." (PMID 20957146, 2010). "Since many viruses reprogram cellular metabolism to support viral replication, we performed a comparative analysis of inhibitors targeting the PI3K/AKT/mTOR pathway, central to virus-induced metabolic adaptations, using MRC5 lung fibroblasts and Huh7 hepatoma cells." (PMID 41155146, 2025). "Furthermore, our previous in vitro studies reported that CuD, CuI, and CuE significantly increased the apoptosis rate by suppressing oncogenic signaling pathways (Jak/Stat, PI3K/Akt/mTOR, MAPK/ERK) that show abnormal activity in hepatocellular carcinoma." (PMID 40678417, 2025). "It is therefore conceivable that a similar inhibitory mechanism of the Rheb/mTOR axis, as depicted in HSC cells, may function in hepatoma cells with activated ERAD, resulting in stimulation of autophagy." (PMID 39838427, 2025). "In hepatoma cells, genetic knockout of CD147 reduced fatty acid synthesis by disrupting the Akt/mTOR signaling pathway and upregulating peroxisome proliferator-activated receptor α (PPARα), thereby increasing proliferation and metastasis formation in cell lines and mouse models." (PMID 40881692, 2025). "In hepatocellular carcinoma, PRMT4 exerts its effects by activating the AKT/mTOR pathway." (PMID 40869229, 2025). "Conversely, E2F1 also functions as a suppressor in hepatocellular carcinoma, interacting with ubiquitin specific peptidase 11 (USP11) to regulate the extracellular-signal regulated protein kinase/mammalian target of Rapamycin (ERK/mTOR) pathway to inhibit autophagy." (PMID 40886002, 2025). "However, when mTOR is activated, it decreases the sensitivity of AT406 and leads to drug resistance in hepatocellular carcinoma." (PMID 38338834, 2024). "As this signaling pathway is activated by CCL20 in hepatocellular carcinoma (HCC), it could be assumed that this occurs in melanoma cells as well, particularly CCL20 signals via the PI3K/AKT/mTOR pathway." (PMID 38730689, 2024). "Additionally, sorafenib in combination with capsaicin downregulated the expression levels of Akt, mTOR, and p70S6K in LM3 human hepatocellular carcinoma cells, thereby inducing apoptosis." (PMID 38527038, 2024). "By activating the PTEN/AKT/mTOR pathway, fibrinogen may induce EMT and facilitate hepatoma metastasis." (PMID 39859975, 2024). "mTOR expression is high in patients with hepatocellular carcinoma (HCC) that have vessels that encapsulate tumor clusters, suggesting that the mTOR inhibitor, everolimus, could be particularly affective in patients with HCC being treated using living donor liver transplantation." (PMID 38250695, 2024). "By activating the (protein kinase B) AKT/mTOR (mammalian target of rapamycin) pathway and promoting epithelial–mesenchymal transition (EMT), fibrinogen may simultaneously encourage hepatoma cell motility and invasion." (PMID 39859975, 2024). "Met could transcriptionally down-regulated the expression of MDR1 by modulating AMPK/mTOR pathway and inhibiting HIF-1α expression, leading to reverse multidrug resistance in hepatocellular carcinoma." (PMID 37828612, 2023). "In vitro experiments have shown that quercetin may partially inhibit AKT/mTOR pathway and activate the MAPK pathway, thus stimulating autophagy and inducing hepatocellular carcinoma cell apoptosis." (PMID 36043445, 2023).
hepatocellular carcinoma (continued). "Another compound isolated from Sinularia flexibilis, 11-epi-sinulariolide acetate (11-epi-SA, 8 μM), inhibited the migration and invasion of HA22T hepatocellular carcinoma cells coinciding with reduced p-ERK1/2 and p-p38 protein levels along with reduced p-AKT, p-PI3K, and p-mTOR expression." (PMID 38132936, 2023). "These bromobenzofuran-oxadiazole structural hybrids BF1-9 were evaluated in vitro against anti-hepatocellular cancer (HepG2) cell line as well as for their in silico therapeutic potential against six key cancer targets, such as EGFR, PI3K, mTOR, GSK-3β, AKT, and Tubulin polymerization enzymes." (PMID 36769327, 2023). "PCK1 is downstream of the mTOR pathway; mTOR inhibition up-regulates PCK1 and shuttles glycolytic flux to the gluconeogenesis pathway, thereby inhibiting cellular proliferation in hepatocellular carcinoma and ccRCC." (PMID 37062825, 2023). "Artemisinin inhibited the proliferation and promote apoptosis of hepatocellular carcinoma cell lines Huh7 and SMMC-7721 by inhibiting the phosphorylation of Akt and S6 in mTOR signaling pathway of Huh7 cells and the phosphorylation of C-myc and S6 in mTOR signaling pathway of SMMC-7721 cells." (PMID 35646647, 2022). "Upregulated miR-29-3p could inhibit hepatocellular carcinoma cell proliferation, migration, invasion, and metastasis through inhibition of Robo1 and inactivation of the PI3K/Akt/mTOR signaling pathway." (PMID 36430972, 2022). "Carrimycin may exert its function through PI3K/AKT/mTOR pathway and MAPK pathway in oral squamous cell carcinoma cells, while suppressing tumor growth of hepatocellular carcinoma by inhibition of VEGF and PD-L1 protein expression." (PMID 35387667, 2022). "In addition, puerarin 6’-O-xyloside, an analog of puerarin, suppressed hepatocellular carcinoma by regulating proliferation, stemness, and apoptosis by inhibiting PI3K/Akt/mTOR." (PMID 34863080, 2021). "In addition, miR-144 could inhibit human hepatocellular carcinoma by regulating CCNB1, repress the mTOR-VEGF pathway by targeting SGK3 in HCC, and reverse the chemoresistance of HCC cells by suppressing Nrf2." (PMID 33526055, 2021). "mTOR expression was not significantly changed in MHCC-97L hepatoma cells treated with radiation or SSd alone, but p-mTOR expression was lower than that in the control group; in the radiation and SSd co-treatment group, p-mTOR expression was further reduced." (PMID 33628104, 2021). "In addition, TINCR expression is up-regulated in hepatocellular carcinoma, resulting in activation of the phosphoinositide 3-kinase (PI3K)–Akt–mechanistic target of rapamycin (mTOR) signaling pathway through sequestration of the microRNA miR-7-5p." (PMID 34351912, 2021). "PKI-587 inhibited proliferation, promoted apoptosis, and enhanced radiosensitization of hepatocellular carcinoma cells by blocking abnormal, radiation-induced activation of the PI3K/AKT/mTOR and DNA damage repair pathways and their downstream effector molecules." (PMID 34665844, 2021). "Activated AKT stimulates the mTOR transcription cofactor and the STAT3 and HIF-1α transcription factors, which regulates the expression of oncogenes, inhibits apoptosis and inhibits autophagy in hepatoma cells as well as promotes the growth of cancer cells." (PMID 33898423, 2021). "Importantly, they showed that knockdown of LINC01554 suppressed the proliferation and metastasis via suppressing the Akt/mTOR signaling pathway, suggesting LINC01554 as an oncogenic lncRNA in hepatocellular carcinoma." (PMID 34422133, 2021). "Therefore, SSd promotes radiation-induced autophagy in hepatoma cells, and increased expression of LC3-II can be reversed by mTOR agonists." (PMID 33628104, 2021).
hepatocellular carcinoma (continued). "As a result of hypoxia-induced energy metabolism reprogramming, the augmented PDK1 expression in hypoxic tumors can drive the PI3K/Akt/mTOR signaling that promotes the EMT and formation of the radioresistant CSC-like phenotype, as it was shown for PDK1-overexpressing hepatocellular carcinoma." (PMID 33806538, 2021). "The addition of the autophagy inhibitor chloroquine (CQ) or an mTOR agonist (MHY1485), which could reduce the promoting effect of SSd on radiation-induced apoptosis and inhibitory effect on the proliferation of hepatoma cells." (PMID 33628104, 2021). "Similarly, in the study of hepatocellular carcinoma, glycochenodeoxycholate induces AMPK/mTOR-dependent autophagy activation, which in turn promotes cell invasion and migration." (PMID 34692659, 2021). "In another study, the interaction of FGFR4 with the βKlotho (KLB) co-receptor, a metabolic regulator that is frequently disrupted in hepatic cancers, was shown to inhibit cell proliferation and induce caspase-3-dependent apoptosis in hepatomas by decreasing AKT and mTOR activity." (PMID 34830951, 2021). "The mTOR inhibitor rapamycin does not inhibit the TPA-induced PDCD4 suppression in Huh7 hepatoma cells." (PMID 31075975, 2019). "Furthermore, in hepatocellular carcinoma cells or aggressive B-cell lymphomas, high eIF4E/4E-BP1 confers resistance to metformin-induced apoptosis or mTOR inhibitors, respectively." (PMID 30138450, 2018). "However, miR-199a-3p is frequently downregulated in hepatocellular carcinoma, where it targets PAK4, CD44, and mTOR [14, 15, and 16] and displays antiproliferative/tumor suppressor functions." (PMID 25839163, 2015). "Collectively, these findings suggested that metformin may target the AMPK/mTOR/HIF-1α/P-gp and MRP1 pathways to reverse MDR in hepatocellular carcinoma." (PMID 25310259, 2014). "Inhibition of mTOR activity in human hepatoma cells reduced HIFα expression without reducing its mRNA or promoting its degradation." (PMID 24804240, 2014). "Our results suggest that dual targeting of mTOR and AKT might be a new promising therapeutic approach in the treatment of hepatocellular carcinoma." (PMID 23167739, 2012). "Therefore, we designed a prospective RCT to determine if the mTOR inhibitor sirolimus can improve hepatocellular carcinoma (HCC)-free patient survival in liver transplant (LT) recipients with a pre-transplant diagnosis of HCC." (PMID 20459775, 2010). "Thus, modulation of PI3K/AKT/mTOR pathway through enhanced PTEN, as well as reduced β-catenin/BCL2 and β-catenin/HSP90 expression leads to significantly better survival probability in hepatocellular carcinoma samples." (PMID 40456804, 2025). "Previous studies have demonstrated that ZZXJD induces autophagy and apoptosis in hepatocellular carcinoma cells via the AKT/mTOR and JAK2/STAT3 signaling pathways, resulting in programmed cell death and inhibition of HCC progression." (PMID 40303917, 2025). "In hepatocellular carcinoma (HCC), CD71 promotes cancer progression via mTOR signaling and correlates with poorer overall survival and disease-free survival." (PMID 41375568, 2025). "In a study on hepatocellular carcinoma (HCC), the high-mobility group box 1 gene (HMGB1) and the important molecule RICTOR in the mTOR pathway competitively bound to members of the miR-200 family, especially miR-429." (PMID 38302430, 2024). "Furthermore, Zhou and colleagues in their investigation approved that in hepatocellular carcinoma cells, fibronectin type III domain-containing protein 5 stimulates autophagy through the AMPK/mTOR signaling pathway, which adds to the chemoresistance to nab-paclitaxel." (PMID 39315094, 2024). "In hepatocellular carcinoma cells (HCC), miR-1307-3p increased proliferation and invasion under hypoxia conditions by downregulating DAB2IP to activate AKT/mTOR and increase HIF-1α expression." (PMID 38902547, 2024).
hepatocellular carcinoma (continued). "Trillin inhibits autophagy and promotes apoptosis in hepatocellular carcinoma cells through activation of the mTOR/STAT3 signaling pathway, suggesting its potential as a therapeutic agent for HCC." (PMID 39315094, 2024). "The AMPK activation by metformin enhances the binding of DEPTOR and mTOR by increasing DEPTOR production and inhibiting proteasomal degradation, thereby interfering with the downstream target p70-S6 kinase and ribosomal protein S6 and inhibiting the proliferation of hepatocellular carcinoma cells." (PMID 38192642, 2023). "Also, flaccidoxide-13-acetate reduced the cellular viability (8 μM, 24 h) and the migration/invasion (4–8 μM, 24 h) of HA22T and HepG2 hepatocellular carcinoma cells; these cellular responses were accompanied by reduced protein levels of p-PI3K, p-AKT, and p-mTOR." (PMID 38132936, 2023). "The cellular mechanism of widespread activation of the PI3K/Akt/mTOR pathway in hepatocellular carcinoma is not completely clear, but inhibition of PI3K/AKT/mTOR can prevent abnormal cell proliferation, cell metabolism and tumor angiogenesis, thus providing potential molecular targeted therapy." (PMID 36374212, 2022). "The results are similar in hepatocellular carcinoma (HCC), as cancer cells grow faster in FGL1-null mice, which is related to the activation of Akt and mTOR signal pathways." (PMID 36358792, 2022). "Our results showed that the expression of mTOR was not significantly changed in MHCC-97L hepatoma cells treated with radiation or SSd alone; however, the expression of p-mTOR was lower than that in the control group, especially in the radiation and SSd co-treatment group." (PMID 33628104, 2021). "Linalool is a promising anticancer agent for hepatocellular carcinoma (HCC) therapy via inducing cell apoptosis via Ras, Mitogen-activated protein kinase (MAPKs), and the protein kinase B (AKT)/mammalian target of rapamycin (mTOR)pathways." (PMID 33126443, 2020). "On the contrary, in hepatocellular carcinoma (HCC) cells, the induction of the PI3K/Akt/mTOR pathway by α-fetoprotein (AFP) resulted in reduced cell autophagy and more malignant behavior." (PMID 30609663, 2019). "A previous study showed down-regulating TIP30 activated the Akt/mTOR signaling pathway to up-regulate SREBP1 expression, which promoted lipid metabolism by activating gene transcription of lipogenesis, including FASN and SC, promoting proliferation of hepatocellular cancer cells." (PMID 31299935, 2019). "In hepatocellular carcinoma (HCC), miR-1207-5p inhibits HCC cell growth and invasion by suppressing the AKT/mTOR signaling pathway through fatty acid synthase inhibition." (PMID 30464258, 2018). "In hepatocellular carcinoma cells (HCC), the PI3K/Akt/mTOR pathway and the Ras/Raf/MEK/ERK pathway have a synergetic relationship in regulating the proliferation of tumor cells." (PMID 27654866, 2016). "For example, mTOR signaling may be activated by the upregulation of MMP-9 but not by that of MMP-2 in hepatocellular carcinoma." (PMID 26202311, 2015). "Therefore, in this study, we wanted to investigate the antitumor activity of the orally bioavailable dual PI3K/mTOR inhibitor, NVP-BGT226 (BGT226), on a panel of hepatocellular carcinoma (Mahlavu, SNU475, SNU449, HepG2 and Hep3B) cell lines in either normoxia and hypoxia condition." (PMID 26003166, 2015). "Results showed that its anti-malignancy activities were activated by mTOR/S6K1, cyclinD1/CDK2/4 and caspase-dependent apoptotic signaling pathways in hepatocellular carcinoma cells (HCC)." (PMID 25486097, 2014). "The current study aimed to investigate the expression levels of c-erb-B2, EGFR, PTEN, mTOR, PI3K, p27, and ERCC1 in hepatocellular carcinoma (HCC) and their correlation with other clinicopathologic features." (PMID 23162604, 2012).
hepatocellular carcinoma (continued). "In hepatocellular carcinoma (HCC), SIRT1 deacetylates p62 at K295, preventing its degradation, activating mTORC1, and promoting hepatocarcinogenesis, while PCAF enhances autophagic flux by inhibiting Akt/mTOR, thereby inducing cancer cell death." (PMID 41213956, 2025). "Specifically, bile acid and sphingolipid metabolites activate the hepatocellular carcinoma MAPK/mTOR pathway, subsequently leading to lipid metabolism disorders in HCC – a phenomenon not previously reported." (PMID 38773448, 2024). "LYC lowers the levels of tongue cancer and Hepatocellular Carcinoma (HCC) cells TCRP1 protein by promoting the degradation pathway of TCRP1 protein, which translates into repression of Akt/mTOR signaling, and therefore activates apoptotic and autophagic abilities." (PMID 38572428, 2024). "However, long-term studies using mTOR inhibitors in these mouse models will be needed to provide further evidence of the relationship between NOX activation and ROS generation and subsequent mTOR activation and development of hepatocellular carcinoma from NASH." (PMID 31614491, 2019). "In contrast to previous studies reporting that linalool inhibits AKT/mTOR signaling in human oral cancer OECM 1 cells and hepatoma HepG2 cells, we did not detect a suppression of AKT phosphorylation in linalool-treated HDMECs." (PMID 33655414, 2021). "The Akt/mammalian target of rapamycin (mTOR) and the extracellular signal‐regulated kinase 1/2 (ERK1/2) pathways are both involved in nutrient‐induced autophagic phenomenon and exhibit vital relevance to oncogenesis in various cancer cell types, including hepatocellular carcinoma (HCC)." (PMID 28675698, 2017). "Similarly, GDF11 also activated non-Smad (e.g., AMPK, MAPK, mTOR, PI3K) pathways in a wide range of cell types, such as cardiomyocytes, neural stem cells, human hepatocellular carcinoma cells, primary hepatocytes, and mesenchymal stem cells." (PMID 36293138, 2022). "Similar to the present results, although rapamycin, an inhibitor of mTOR, alone did not induce senescence in the SMMC-7221 hepatocellular carcinoma cell line, its combination with 5-FU, an anti-metabolite, induced senescence and exerted synergistic anti-tumor effects." (PMID 35406478, 2022). "Our previous study of hepatoma Huh-7 cells revealed that 7-KC distributed mainly in the non-lipid raft domains in 7-KC-treated cells and PI3K/mTOR signaling is crucial for the post-transcriptional induction of P-gp by 7-KC, whereas the oxidative stress made a minimal contribution." (PMID 29029490, 2017).